HAVCR2 (hepatitis A virus cellular receptor 2)
Diseases named in the same sentence as HAVCR2 in open-access papers (continued):
Sharing a sentence is not in itself a finding about the gene and the disease.
glioma (continued). "Hence, HAVCR2 is a potential biomarker for the diagnosis, treatment, and prognosis of gliomas and should be developed further as a therapeutic target for antiglioma immunotherapies." (PMID 35198632, 2022). "Altogether, these findings suggested that glioma patients might benefit from HAVCR2- or PDCD1LG2-based immunotherapies." (PMID 35198632, 2022). "HAVCR2 can be a potential therapeutic target for cancer immunotherapy for glioma patients." (PMID 35198632, 2022). "Similarly, HAVCR2, a gene encoding TIM-3, was positively correlated with the expression of LINC00324, which may regulate immune activity through the GALECTIN signaling pathway in the glioma immune microenvironment." (PMID 38530810, 2024). "In addition to PD-1, CTLA-4, and IDO, other immune checkpoints are also involved in the occurrence and development of glioma, including T cell membrane protein-3 (TIM-3; also known as HAVcr2), killer inhibitory receptors (KIR), and V-domain Ig-containing suppressor of T cell activation (VISTA)." (PMID 27756892, 2017). "We also observed positive correlations between the risk score and several immune checkpoint genes, including SIGLEC7, PDCD1, LILRB2, HAVCR2, and LAG3, which have been tied to poor prognosis in glioma." (PMID 41180518, 2025). "Immune checkpoint genes such as PD-L1, PD-1, CTLA4, LAG3, HAVCR2, PDCD1LG2 were positively correlated with IGFBP5 in glioma." (PMID 38164271, 2024). "Here, through the analysis of 11 commonly studied checkpoint and inhibitory receptors, we discern that only HAVCR2 (TIM3) and ENTPD1 (CD39) display significantly greater gene expression in glioblastoma compared to normal brain and lower grade glioma." (PMID 39513882, 2024). "Our data revealed a significant correlation between the expression levels of immune checkpoint molecules (CD274, CTLA4, HAVCR2, LAG3, PDCD1, PDCD1LG2, TIGIT, and SIGLEC15) and RAB32 in high-grade gliomas (HGG)." (PMID 39668831, 2024). "HAVCR2 is widely expressed in GBM and IDH-WT gliomas and is able to regulate the inflammatory response after anti-PD-1 treatment." (PMID 36321611, 2023). "We observed that PTPN18 expression was positively correlated with six immunosuppressive genes (PD-L1, PD-1, CTLA4, LAG3, HAVCR2, and CD244) in most cancers, including glioma." (PMID 36846716, 2023). "We further analyzed the expression distribution of immune checkpoints gene (including CD274, CTLA4, HAVCR2, LAG3, PDCD1, PDCD1LG2, TIGIT, and SIGLEC15) in glioma tissues and normal brain tissues using the TCGA database." (PMID 36915038, 2023). "MAPK4 expression was significantly positively correlated with expression of the main immunoinhibitory checkpoint molecules PD‐1, PD‐L1, HAVCR2, PDCD1LG2 and TIGIT in glioma." (PMID 36999945, 2023). "Immunohistochemistry was used to assess PTX3 expression, HAVCR2, PD‐1, PD‐L1, and CD276 in glioma sections from the Xiangya cohort (n = 60)." (PMID 35855654, 2022). "The highest expression was detected in the WHO glioma grade IV tumors (CD274 p = 2.0e − 08, HAVCR2 p = 1.5e − 09, LAG3 p = 9.7e − 05, PDCD1 p = 5.6e − 05, PDCD1LG2 p = 2.2e − 18, and SIGLEC15 p = 4.3e − 05)." (PMID 35198632, 2022). "We investigated the immune checkpoint expression in glioma specimens and uncovered that CD274 (PD-L1), PDCD1, PDCD1LG2, CTLA4, CD276, HAVCR2, and LAG3 were significantly overexpressed in the high DDR score subtype." (PMID 35720326, 2022). "It is found that the expression of PROS1 had positive correlations with PD-1, PD-L1, PDCD1LG2, CTLA4, HAVCR2, and GZMB (all P <0.05) in glioma." (PMID 36685506, 2022). "Based on the TCGA and CGGA datasets, we proved that PTX3 positively correlated with CD276, CD274, PDCDL1LG2, HAVCR2, CD80, IDO1, and PDCD1 in pan‐glioma, GBM, and LGG." (PMID 35855654, 2022). "B2M exhibited a highly positive correlation with immune checkpoint molecules, such as PDCD1LG2, HAVCR2, CD274 in pan-gliomas and LGG samples, respectively." (PMID 33658560, 2021).
glioma (continued). "Other immune checkpoints that are targeted by drugs for clinical use, including B7H3 (CD276) and TIM3 (HAVCR2), were also found to be highly expressed in patients with high-HIF1A-expression gliomas." (PMID 34305618, 2021). "PDIA3 was highly positively correlated with HAVCR2, CD274, PDCD1LG2 and others in pan-gliomas and LGG and GBM samples, and PDIA3 demonstrated a high positive correlation with PDCD1LG2 in GBM." (PMID 32687065, 2020). "Through high-throughput expression profiling, WGCNA, lasso, and multivariate Cox analysis, we acquired eight genes (HCK, HAVCR2, CD37, LPAR5, NAGA, C1QC, FCER1G and AIF1) to construct the MRGs signature in Grade II/III glioma patients." (PMID 33186124, 2020). "In glioma cells, it was observed that the expression of genes related to MRM, like GTPBP3, METTL2A, METTL6, METTL8, NSUN4, and TRMT61A, showed positive correlation with the expression of HAVCR2, PVR, TNFRSF25 and TNFSF15 as revealed by scRNA-seq analysis." (PMID 38824202, 2024). "Specifically, we found that, as IGFBP5 levels increased, the expression of the seven immune checkpoint genes (BTLA, CD274, CTLA4, HAVCR2, LAG3, PDCD1, and PDCD1LG2) were increased and a large positive correlation was observed between IGFBP5 and these immune checkpoints in glioma." (PMID 38164271, 2024). "The expression of HAVCR2, PVR, TNFRSF25, and TNFSF15 showed a positive correlation with the expression of numerous MRM-related genes like GTPBP3, METTL2A, METTL6, METTL8, NSUN4, and TRMT61A in glioma cells." (PMID 38824202, 2024). "Indeed, the expression of A3C displayed positive correlations with CD274, PDCD1, PDCD1LG2, SIGLEC15, CTLA4, HAVCR2, and GZMB in glioma (P < 0.05)." (PMID 37809064, 2023). "Based on TCGA and CGGA datasets, we observed a high and positive correlation between TNFSF13 and PDCD1LG2, HAVCR2, CTLA4, and other checkpoint molecules in pan-gliomas, LGG and GBM analysis, and TNFSF13 expression is tightly correlated with HAVCR2 in glioblastomas." (PMID 34712225, 2021). "Results refer thatMLLT11 had a highly negative correlation with PDCD1, PD-L1, TIM3(HAVCR2), and PD‐L2 (PDCD1LG2) in grade 3 glioma analysis." (PMID 36033495, 2022). "In TCGA datasets, among WHO grade 3 glioma,MLLT11 showed a highly negative correlation with PD-1 (r = -0.34, p = 8.3 × 10-28), PD-L1 (r = -0.41, p = 3.5 × 10-11), TIM3(HAVCR2) (r = -0.4, p = 1.2 × 10-11), and PD‐L2 (PDCD1LG2) (r = -0.58, p < 2.2 × 10-16)." (PMID 36033495, 2022). "Thus, we attempted to analyze certain immune checkpoints such as CD274 (PDL1), CD48, and HAVCR2 (TIM-3), which have been proven to play negative roles in gliomas." (PMID 40606983, 2025).
breast cancer (129 papers, 2013 to 2026). A primary or metastatic malignant neoplasm involving the breast. "In previous studies, the significant associations of heterozygous genotype of PDCD1 rs2227982 and HAVCR2 rs13170556 with the risk for breast cancer and the outcomes of HCV infection were reported, respectively." (PMID 38723011, 2024). "The first study attempting to examine relations between the HAVCR2 gene polymorphisms and susceptibility to breast cancer were carried out on 560 BC patients and 583 control subjects of Northwest China descent." (PMID 33519815, 2020). "Overexpression of TIM-3/HAVCR2 is associated with poor prognosis in squamous cell carcinoma, colorectal, renal cell carcinoma, gastric, and breast cancers." (PMID 35774505, 2022). "Overexpression of TIM-3/HAVCR2 is associated with a poor prognosis in squamous cell carcinoma, and in colorectal, gastric and breast cancers." (PMID 29796301, 2018). "In addition, pDCs and CD8+ T cells were also found to express HAVCR2 in high expression and CD4+ T cells in lung cancer, while CD4+ T cells in breast cancer and colorectal cancer expressed HAVCR2 significantly lower than CD8+ T cells." (PMID 39120585, 2024). "Moreover, the expression of LAG3, CTLA-4, PD-L1, CD274, TIGIT, HAVCR2 and PDCD1LG2 was upregulated in the TFRC high-expression group compared with the TFRC low-expression group in breast cancer." (PMID 35847985, 2022). "The results showed that in breast cancer, GPS1 expression was positively correlated with LAG3, PVRL2, and LGALS9, and negatively correlated with CD274 and HAVCR2, but not with CTLA4 and PDCD1." (PMID 38289496, 2024).
hepatocellular carcinoma (116 papers, 2013 to 2025). A malignant tumor that arises from hepatocytes. "The most significant immune biomarkers for hepatocellular carcinoma were employed in immunotherapy, according to earlier research: PDCD1, CTLA4, HAVCR2/TIM3, and LAG3." (PMID 38248311, 2023). "Similarly, another study in hepatocellular carcinoma identified UBASH3B as a central component of the immunosuppressive signaling axis involving NRI1I2, CEACAM1, and HAVCR2." (PMID 40885971, 2025). "Such as in nonsmall cell lung cancer (NSCLC) as well as hepatocellular carcinoma (HCC), a malfunction CD8 + T cell population was discovered to be positively related to high levels of expression of suppressor receptor genes (PD1, PD-L1, LAG3, CTLA4, TIGIT, and HAVCR2)." (PMID 35845137, 2022).
COVID-19 (110 papers, 2020 to 2026). A disease caused by infection with severe acute respiratory syndrome coronavirus 2. "On the other hand, the inflammatory NOTCH2-IL24 interaction which induces STAT1 and STAT3 to regulate cell proliferation and survival and the inhibitory interactions CTLA4-CD86 and HAVCR2-LGALS9 were unique to patients with COVID-19." (PMID 36992700, 2023). "Moreover, some regulatory and tissue repair-associated genes (CD163, IL1R2, AREG, HAVCR2 (encoding TIM-3), and its ligand LGALS9) and pathways (TIM-3/Gal-9 pathway) were found up-regulated in progressive COVID-19 patients." (PMID 37795081, 2023). "Additionally, the expression of transcripts regulating cellular exhaustion (TIGIT, BTL4, PDCD1, and HAVCR2) was found to be similarly upregulated in severe COVID-19." (PMID 37029220, 2023). "Among the co-inhibitory receptors, LAG3, CTLA4, and HAVCR2 were enriched in CD8+ T cells from COVID-19 patients that eventually succumbed to the disease, but PDCD1 and TIGIT were enriched in CD8+ T cells from COVID-19 patients that eventually recovered and discharged." (PMID 36119105, 2022). "Another study also identified other cell exhaustion markers (LAG3, PDCD1 and HAVCR2) on NK cells from COVID-19 patients which could reflect that SARS-CoV-2 infection could induce these phenotypes in COVID-19 patients." (PMID 36369012, 2022). "Interestingly, we detected a small population of exhausted CD8+ T cells (TEX) characterized by expression of TIGIT, CTLA4, CD279 (PD-1) and HAVCR2 (Tim-3) that was exclusive to the severe COVID-19 group, a finding which has been reported by others before." (PMID 36591270, 2022). "Another study suggests that the expression of T-cell immunoglobulin mucin-3 (TIM-3, also named HAVCR2) and lymphocyte-activation gene-3 (LAG3) in patients with more severe COVID-19 is much higher than that in patients with mild disease." (PMID 37932287, 2023). "The activated and effector status of NK cells has been also confirmed in BALF as GZMB, GZMA, PRF1, HAVCR2 (Tim-3), and CCL4 are upregulated in COVID-19 patients compared to controls." (PMID 35844604, 2022). "S2, C and D) were also identified as DEGs in BAL NK cells of COVID-19 patients as compared with controls, including GZMB (granzyme B), PRF1 (perforin), HAVCR2 (Tim-3), and CCL4 (MIP-1β)." (PMID 32826343, 2020). "Namely, we found an enrichment of two COVID-19-unique inhibitory interactions between APCs and CD8+ T cells, CTLA4/CD86 and HAVCR2/LGALS9, which may be out of necessity to curb the heightened inflammation present in severe COVID-19." (PMID 36992700, 2023). "Furthermore, the inhibitory membrane receptors expressed by CD8+ T cells, such as PDCD1 (PD1), CTLA4, and HAVCR2 (TIM3), were significantly upregulated in severe COVID-19 patients when compared with those in healthy people and mild COVID-19 patients." (PMID 34305939, 2021). "Interestingly, the Macro/T cell type which may be “doublets” of macrophages and T cells and expressed exhaustion markers such as LAG3 and HAVCR2, only existed in BALF of severe COVID-19." (PMID 35694714, 2022). "In addition, T cells exhaustion was observed in severe COVID-19 patients but not in the RP or MM COVID-19 patient, as supported by the distinct expression pattern of T cells exhaustion-related genes such as programmed cell death 1 (PD-1, PDCD1) and Tim-3 (HAVCR2)." (PMID 34305895, 2021).
lung cancer (99 papers, 2012 to 2026). A malignant neoplasm involving the lung. "In addition, the CXCL13+CD4+ T cell subset indicated in lung cancer has been described by high expression of exhaustion markers, including PDCD1, CTLA4, TIGIT, and HAVCR2, which is considered as an exhausted CD4+ T cell subpopulation." (PMID 37187731, 2023).
leukemia (91 papers, 2013 to 2025). A malignant (clonal) hematologic disorder, involving hematopoietic stem cells and characterized by the presence of primitive or atypical myeloid or lymphoid cells in the bone marrow and the blood. "Given the strong induction of GAL-9 in ACM-exposed human B-ALL cell lines, we next mined publicly available databases to examine the expression levels of LGALS9 (the gene encoding GAL-9) and HAVCR2 (the gene encoding TIM-3) in leukemia cells from patients at diagnosis and relapse." (PMID 35241678, 2022). "HAVCR2 regulates T-cell depletion and acts as an immune checkpoint in immune escape and immunotherapy of leukemia." (PMID 39422621, 2024). "In contrast, HAVCR2 was expressed at lower levels in leukemia patient samples than observed in PBMCs." (PMID 35241678, 2022). "These proteins included the myeloid differentiation marker CD86 and the leukemia cell-specific HAVCR2/TIM-3." (PMID 31336716, 2019). "Several genes upregulated in the TF1a dormancy model have been described in leukaemia initiating cells, but appear not to be crucial for maintenance of normal HSCs, e.g. CD44, ITGB3, TIM3 (HAVCR2) and IL3RA." (PMID 29340063, 2017).
acute myeloid leukemia (88 papers, 2012 to 2026). Acute myeloid leukemia (AML) is a group of neoplasms arising from precursor cells committed to the myeloid cell-line differentiation. "HAVCR2 was reported to be abnormally expressed in T-cell lymphoma, acute myeloid leukemia, hepatitis A and injured nerve tissue." (PMID 32140464, 2020).
autoimmune disease (86 papers, 2009 to 2026). A disorder resulting from loss of function or tissue destruction of an organ or multiple organs, arising from humoral or cellular immune responses of the individual to their own tissue constituents. "On the other hand, findings from HAVCR2 polymorphisms and modulation experiments in autoimmune diseases and IBD, using TIM-3 with blocking antibodies or activation by its ligand galectin-9, rather indicate a predominant inhibitory role, particularly in colitis." (PMID 41483156, 2026). "T cell immunoglobulin-3 (TIM-3, CD366, HAVCR2), serving as a co-inhibitory receptor, is involved in the immune regulation of autoimmune diseases, transplantation tolerance, tumors, and infectious diseases." (PMID 40861801, 2025). "In humans, single nucleotide polymorphisms (SNPs) in the coding and noncoding regions of the TIM-3 gene, also known by the gene name HAVCR2 (hepatitis A virus cellular receptor 2), have been linked to several allergic and autoimmune diseases." (PMID 33171904, 2020). "Overall, the results from genetic modifications of HAVCR2 show that impaired TIM-3 function leads to dysregulated immune activation and increased proinflammatory cytokines, which is also frequently observed in autoimmune diseases." (PMID 41483156, 2026).
viral infection (76 papers, 2010 to 2025). "In contrast, the exhausted genes were up‐regulated after viral infection (e.g. Havcr2, Lag3, Cd96 and Ctla4)." (PMID 35051311, 2022). "Regarding anti-inflammatory genes, HAVCR2 was upregulated; it reduces cytokines, chemokines, prostaglandins, and cell adhesion molecules in the presence of viral infections." (PMID 35095855, 2021). "Genes in this signature code for proteins that are viral infection restricting factors (e.g. Ifitm1, Ifitm3, Gbp7), that protect against cellular or environmental stress (e.g. Abcb1a, Car2, Ern1, Serpina3g) or that regulate immune activation processes (e.g. Fgl2, Anxa1, Havcr2)." (PMID 27883012, 2016). "Several research papers suggest that expression of co-inhibitory molecules such as PDCD1 (PD-1), HAVCR2 (Tim-3), CTLA4, and LAG3 correlates with the activated and more differentiated state of CD8+ T cells in viral infection." (PMID 37409113, 2023).
gastric cancer (70 papers, 2013 to 2026). A primary or metastatic malignant neoplasm involving the stomach. "For instance, in gastric cancer, elevated HAVCR2 expression in tumour tissues is associated with poor prognosis." (PMID 38568056, 2024). "HAVCR2 was a prognostic biomarker for gastric cancer and was negatively associated with OS, and two independent studies revealed that HAVCR2 was a diagnostic and prognostic biomarker of osteosarcoma and large B-cell lymphoma." (PMID 34336706, 2021). "The association between HAVCR2 genetic variants and the risk of gastric cancer (GC) development was published in 2010 by Cao at al." (PMID 33519815, 2020). "High THSD7A expression suppressed the sensitivity of patients with gastric cancer to drugs, such as 5-fluorouracil, bleomycin, and cisplatin, and upregulated immune checkpoints, such as HAVCR2, PDCD1LG2, TIGIT, and CTLA4." (PMID 37905960, 2023). "Meanwhile, high expression of HAVCR2 was significantly correlated with the poor prognosis of ovarian cancer, colon cancer, bladder urothelial carcinoma, and gastric cancer." (PMID 34733794, 2021). "The immune checkpoint analysis indicated that gastric cancer patients with upregulated GGT5 expression showed a higher TIDE score and expression of CD274, CTLA4, HAVCR2, LAG3, PDCD1, PDCD1LG2, and TIGIT than patients in the GGT5-low expression group." (PMID 35368661, 2022). "The research results indicated that there exists a significant positive correlation between DLX2 and CTLA4, PDCD1, HAVCR2 and TIGIT, which may contribute to the gastric cancer cells’ ability to evade immune system attacks." (PMID 41244921, 2025).
colorectal cancer (65 papers, 2015 to 2025). A primary or metastatic malignant neoplasm that affects the colon or rectum. "IFNG and HAVCR2 gene expression, which were augmented, best defined Th1-like T cells in colorectal cancer, while PDCD1, an immune checkpoint inhibitor, was decreased." (PMID 31191543, 2019). "This subpopulation was significantly different from the transition-state CD8+ Texint cells, characterized by high Cx3cr1 expression, and terminally exhausted CD8+ Texterm cells, which highly expressed Entpd1 and Havcr2 in colorectal cancer; it was in line with the results of related studies." (PMID 40236705, 2025). "Specifically, in MSI colorectal cancers, immune ESTIMATE, HAVCR2 (TIM-3), CD274 (PD-L1), LAG3 (LAG-3), and PDCD1 (PD-1) each showed significant inverse correlations with GALNT7 expression across the three cohorts." (PMID 40824763, 2025). "This cell state displayed activation (CXCL13) and exhaustion (LAG3, HAVCR2, CD96) markers, which may account for their participation in the immune checkpoint inhibitor sensitivity of MSI-H colorectal cancers." (PMID 35538548, 2022). "TIM-3 (HAVCR2) could be detected in NSCLC, colorectal cancer and HNSC, and served as the predictor to independently predict LC and CRC." (PMID 33324676, 2020). "Upregulation of immune checkpoints HAVCR2/TIM-3 and VISTA in the PRRX1high subgroup is a novel finding, and suggests immune evasion beyond the PD-1/PD-L1 axis, which may contribute to poor response to PD-1/PD-L1–directed immune therapy in MSS colorectal cancer." (PMID 36968142, 2023).